ZNF646 (zinc finger protein 646)
Description:
May be involved in transcriptional regulation.
Synonyms: KIAA0296
Tractability: Antibody: the Human Protein Atlas places it where antibodies can reach. PROTAC: UniProt records ubiquitination sites on it; ubiquitination databases record sites on it.
Gene: Protein-coding gene on chromosome 16 (31,074,403 to 31,084,196, forward strand). Ensembl gene ENSG00000167395.
Subcellular location: Nucleus
Subcellular location (Human Protein Atlas): Cytosol; Nucleoplasm; Plasma membrane
Gene Ontology:
Molecular function: protein binding; DNA-binding transcription factor activity, RNA polymerase II-specific; RNA polymerase II cis-regulatory region sequence-specific DNA binding
Biological process: regulation of DNA-templated transcription; regulation of transcription by RNA polymerase II
Cellular component: nucleus
Genetic constraint (gnomAD): Loss-of-function variants: 45 observed, 102.93 expected, observed/expected ratio (o/e) 0.44, 90% interval 0.34 to 0.56. The upper end of that interval is the gene's LOEUF score, 0.56, which puts it in group 2 of 6, group 1 being the genes least tolerant of losing a copy. Missense variants: 1,948 observed, 2,219.2 expected, observed/expected ratio (o/e) 0.88, 90% interval 0.85 to 0.91. Synonymous variants: 815 observed, 862.71 expected, observed/expected ratio (o/e) 0.94, 90% interval 0.89 to 1.
Homologues: Orthologues: chimpanzee ZNF646 (99% identical), macaque ZNF646 (96% identical), dog ZNF646 (78% identical), rabbit ZNF646 (77% identical), guinea pig ZNF646 (76% identical), rat Zfp646 (70% identical), mouse Zfp646 (69% identical), tropical clawed frog znf646 (34% identical). Paralogues in human: ZNF319 (7% identical), ZNF407 (7% identical), ZNF527 (6% identical), ZNF784 (6% identical), ZNF530 (6% identical), ZNF467 (6% identical), PRDM4 (6% identical), ZKSCAN7 (6% identical), ZBTB17 (6% identical), ZNF287 (6% identical), ZNF398 (6% identical), ZNF416 (6% identical), and 38 more.
Diseases named in the same sentence as ZNF646 in open-access papers:
ZNF646 is named in the same sentence as 2 diseases in open-access papers, as found by Europe PMC text mining. Sharing a sentence is not in itself a finding about the gene and the disease. The quoted sentences say what the papers report.
Obesity (1 paper, 2025). Accumulation of substantial excess body fat. "Interestingly, the CTSB, ZNF646, and KAT8 genes have been associated with obesity." (PMID 40722297, 2025).
ZNF646 also shares sentences with these, for which no sentence is quoted: Alzheimer disease (1 paper).